CD4 (CD4 molecule)
Diseases named in the same sentence as CD4 in open-access papers (continued):
Sharing a sentence is not in itself a finding about the gene and the disease.
infection (continued). "HIV infection in females is marked by a stronger initial immune response, characterized by a high CD4+ T cell count, low viral load and high CD8+ T cell activity, while infection in males is marked by high viral load, a lower CD4+ T cell count and low CD8+ T cell cytotoxic activity." (PMID 37408185, 2023). "Evidence from other immunosuppressive diseases suggests that people with HIV who are getting antiretroviral medication and have healthy CD4 cell counts are not at elevated risk for most infections, including opportunistic infections like mpox." (PMID 37089133, 2023). "Depletion of CD4+ Th cells from PBMCs isolated on day 7 after infection resulted in almost complete loss of IL-17A production in response to stimulation with dmLT and LTB, supporting that the IL-17A responses to LT were derived from CD4+ Th cells." (PMID 37809062, 2023). "CD4+ T cells play an important role in the acute phase of infection." (PMID 37122740, 2023). "Furthermore, type 2 CD4+ST2+ T cell and CD4+Foxp3+ regulatory T cell numbers were also enhanced during infection." (PMID 36602520, 2023). "Thus, the divergence of proviruses can serve as a proxy for the time during infection when the virus was deposited in the CD4+ T cell." (PMID 37961482, 2023). "Additionally, the immunologic damage in the low CD4 group, due to the prolonged period between infection and treatment, is likely to persist despite their increase in CD4 cell counts." (PMID 36996018, 2023). "Since CD4+ T cells expand in female mice following infection, we hypothesized that these T cells might offer protection against CVB3-induced lethality." (PMID 38274806, 2023). "The cytokines produced by the anti-inflammatory CD4+ Th2 cells, which include IL-4, IL-5, and IL-13, lead to the growth of the parasite and the persistence of infection in chronic diseases, in addition to playing a role in the negative regulation of the oxidative burst in infected macrophages." (PMID 37235324, 2023). "H5N1 whole-inactivated virus (WIV) immunization via intranasal and intramuscular route induced a comparable frequency of multifunctional Th1 CD4+ cells, whereas PR8 WIV strain infection induced a higher IFNγ-secreting CD4+ T cells in spleen only in intranasal route." (PMID 36626205, 2023). "The model proposed here has the characteristic of last in first out - the viruses replicating later in infection, which tend to be highly diverged, will be predominantly harbored in short-lived CD4+ T cells, and will be lost earlier than the long-lived cells harboring less diverged proviruses." (PMID 37961482, 2023). "However, the density of CD4+ cells inside the T cell cluster is lower in Duox1 KO at 30 day post infection compared to WT." (PMID 36936954, 2023). "Thus, the available literature suggests that opposing networks of environmental and transcriptional regulators function to maintain the appropriate balance of TFH, TH1, and CD4-CTL effector responses during infection." (PMID 36964178, 2023). "Taken together, these data indicate that altering the infection route by ip injection still generates an expansion of antigen-experienced CD8+ T cells in female Ifnar-/- mice while having little impact on antigen-experienced CD4+ T cells in both sexes." (PMID 37669302, 2023). "Additionally, treatment of aged mice with D + Q followed by flu infection resulted in a significant decrease in Tregs and higher proportion of Th2 CD4 helper cells, which can aid in the resolution of infection." (PMID 37886012, 2023). "Similarly, we found that HLA-DR+CD8+ T cells (including CD8+ Tem, CD8+ Tcm, and CD8+ naive T cells) and CD4+ T cells (especially CD4+ Tem and CD4+ Tcm) were significantly increased in the macaques during infection." (PMID 37033979, 2023). "Similarly, both Foxp3+ and Foxp3− CD4+ T cells produced IL-10 upon infection in IL-4α−/− BALB/c mice." (PMID 38114497, 2023). "The study revealed that VL was a better predictor of Bh infection than CD4+ T cell counts." (PMID 37697423, 2023).
infection (continued). "In addition, the SARS-CoV-2-specific CD4+ T cell response from individuals with a history of natural infection, displayed primarily a TCM phenotype, like previous reports." (PMID 37575243, 2023). "Multivariate logistic regression analysis and ROC curve analysis indicate that circulating EOS (AUC = 0.828, p = 0.025), the combination of EOS and CD4 T cell (AUC = 0.920, p = 0.017) can predict the risk of disease severity in patients with SARS-CoV-2 Omicron BA.2 variant infection." (PMID 37217986, 2023). "In mice, γδ T cells increased in frequency and absolute number in the spleen and lungs after infection, with concomitant increase in absolute numbers of CD4+ and CD8+ T cells, suggesting that γδ T cells could induce the recruitment of T cells after infection." (PMID 38124746, 2023). "Levels of CCR6 + cells were compared between infected and uninfected total CD4 + T cells on day 6 post infection, whether cultured alone or in IEC co-cultures." (PMID 37202790, 2023). "The PD-L2 expression on the macrophages as a result of the eggs laid by the adult worms in the liver was correlated with the PD-1 expression on splenic CD3+CD4+ T-cells, which increased at 3 weeks post-infection and reached a peak at the end of infection at the 12th week." (PMID 36668953, 2023). "Furthermore, particularly after Ag2 stimulation, AIM+CD4+ T cells tended to be higher in subjects with longer time since previous infection and modestly increased with age." (PMID 37220145, 2023). "In support of this notion, previous studies indicated that mucosal DCs can capture HIV-1 through binding of its envelope glycoproteins to CD209 and efficiently transfer the bound virions to CD4+ T cells, in a process called trans-enhancement or trans-infection." (PMID 37542391, 2023). "Our study showed that the major epidemic genotypes were CRF07_BC and CRF01_AE, which was consistent to the prior study.And the distribution of genotype revealed significant differences according to gender, age, education level route of infection, CD4 + T lymphocytes counts and TDR." (PMID 37833806, 2023). "So far, we have seen that IEC promoted productive infection in resting CD4 + T cells." (PMID 37202790, 2023). "Similarly, a positive or negative correlation between SDF1 protein levels and CXCR4 expression in CD4+ TL has been observed, which varied according to the stage of infection." (PMID 36902388, 2023). "This analysis revealed only very minor changes in circulating T cells at the peak of infection — a small increase in expression of CD38 on naive CD4+ T cells and the upregulation of T-bet in CD8+ terminally differentiated effector memory cells re-expressing CD45RA (Temra) and γδ T cells." (PMID 37616070, 2023). "Cell-associated VZV infection of human PBMCs revealed infection of MAIT cells that was at a similar magnitude to non-MAIT CD4+ and CD8+ T cells." (PMID 37006246, 2023). "Interestingly, the frequency of PD-1+ cells was significantly higher within CD4+ T cells throughout the course of the infection." (PMID 37691941, 2023). "Infection with SVNI induced the infiltration of CD4+ and CD8+ T cells, Mo-MΦ, and iNKT cells." (PMID 37168733, 2023). "Similarly, CD4 + Th1 cells have a role in activating CD8 + T under the effect of interferon-γ during infection." (PMID 38072840, 2023). "However, in the late stages of infection, they did mount a normal CD4+ T cell response, a relatively normal CD8+ T cell response, enabling the clearance of LCMV infection to a degree consistent with that of WT mice." (PMID 37251373, 2023). "Therefore, it is plausible that rotavirus-specific CD4+ T cells primed at the site of infection, the gastrointestinal tract, have a unique cytokine production profile or differential trafficking potential, leading to their rarity in circulation." (PMID 37268634, 2023). "Next, we analyzed whether the HIV reservoir parameters before and after breakthrough infection were correlated with baseline CD4 counts." (PMID 38140668, 2023).
infection (continued). "Nevertheless, the effect of this differential DNA methylation on CD4+ T cell gene expression and response to infection remains unclear." (PMID 36922640, 2023). "Mice that have cleared primary infection with attenuated S. Typhimurium become immune and require CD4+ T cells for protection against challenge with virulent S. Typhimurium, while CD8+ T cells and B cell responses likely make additional contributions to overall immunity." (PMID 37733817, 2023). "The proportion of CD4+ T cells increased significantly on the eighth day after infection." (PMID 37585413, 2023). "However, resistance is still potent in mice depleted of CD4+ T cells at the time of secondary infection, indicating that innate memory immune resistance mechanisms require CD4+ T cells for priming but not at the time of secondary challenge." (PMID 37638887, 2023). "At week 4 post infection, CD4+ T-cells showed a mixed response to S. mansoni AWA by secreting cytokines which encompassed Th1 (IFNγ, TNFα, IL-2 & IL-1β), Th2 (IL-4, IL-5, IL-13) and regulatory responses (IL-10) as well as the regulatory T cell transcription factor Foxp3." (PMID 37837930, 2023). "Also in line with our results from pre-patent infection, a significant reduction in expression of Th2 cytokines IL-4, IL-5 and IL-13 was observed in cDC2 depleted Cre+ mice as a proportion of CD4+ T cells, and as absolute number for IL-5 and IL-13." (PMID 37012228, 2023). "BCG induced the biggest GzmB+ CD4+ T cell population and the most pronounced and persistent loss of TCF-1 in all CD4+ T cells, which was evident in ~50% of the cells in the chronic phase of infection." (PMID 37122720, 2023). "Furthermore, a reduced CD4/CD8 ratio is often associated with aging and reduced infection resistance." (PMID 36947105, 2023). "Other studies have shown that CD4+ T lymphocytes may migrate from the cecal tonsils to the bursa, resulting in a decrease in the number of CD4+ T lymphocytes in the cecal tonsils and an increase in the number in the bursa after vvIBDV infection." (PMID 38268928, 2023). "CD4+ T-cell epitopedominance in SARS-CoV-2 spike depends on whether the exposure wasby infection or vaccination." (PMID 37554055, 2023). "The reduced CD4+ T cell responses likely reflect a difference in antigen load between replicating and single-cycle vectors that is much more pronounced during primary infection compared with infection of CMV-immune animals." (PMID 36749635, 2023). "IL-33-responsive CD4+ T cells are also a source of type 2 cytokines in the lungs and are important for memory responses to limit Nb-induced lung damage and worm burden during a secondary infection." (PMID 37251384, 2023). "For example, Leishmania major requires a Th1 response to clear the infection; therefore, in BALB/c mice, where CD4+ T cells differentiate into Th2 cells in response to injury, these cells are unable to control the infection, a result that is detrimental to the host." (PMID 37429945, 2023). "Similarly, the frequency of vaccine-induced S-specific CD4+ T cells is influenced by previous natural infection." (PMID 37575243, 2023). "Infection of CD4+ T cells by SARS-CoV-2 is dependent on CD4 and ACE2 molecules." (PMID 37523305, 2023). "In this study, the proportion of advanced immune suppression (CD4 count < 350 cells/μl) among newly diagnosed long-term infection PLHIV were significantly higher compared to those who were new infections which accounted 47.8% (95%CI = 33.2–52.1) and 30.9% (95%CI = 21.3–42.2), respectively." (PMID 36653851, 2023). "We believe that, had further stratification within each group (PHI and CHI) been carried out based on a period of exposure/infection, it may have provided clearer evidence regarding the differences in terms of CD4+ T-cells in those two groups." (PMID 38005875, 2023). "A rapid decrease in CD4 T cells is evident in rapidly progressing infections after a few years." (PMID 37887742, 2023).
infection (continued). "Furthermore, the temporal increase in the donor CD4+IFNγ+ Tregs indicates replication of these donor Tregs in the recipient mice over the course of the infection as previously reported." (PMID 37965256, 2023). "To uncover the responding CD4+ T cell subsets at the transcriptional level, we performed single‐cell RNA‐seq (scRNA‐seq) and compared PbT‐II cells from anti‐IL‐27 mAb‐ and control IgG‐treated mice on day 7 and 28 after infection (5 and EV3)." (PMID 37855243, 2023). "We observed that LD infection generated a lower Ag+ CD4 and CD8 T cell response at week 2 p.i.." (PMID 36883950, 2023). "We can only speculate, based on reports on murine CD8+ and CD4+ T cells in experimental infection, that augmented IL-2 production in tissue-derived T cells might contribute to more robust memory formation." (PMID 37815874, 2023). "One important factor may be impaired infection control due to slower donor-derived CD4+ T-cell reconstitution after haploHCT." (PMID 37479752, 2023). "Thus, the latently infected and reactivatable resting CD4+ T cell populations established in Fiebig I most plausibly arose from direct infection of this population." (PMID 37733443, 2023). "Because productive infection is strongly impacted by the activation state of a cell, determining if and how CD4-⍺4β7 interactions regulate CD4 participation in TCR-MHC II interactions may help resolve this question." (PMID 38064524, 2023). "Further, lung CD4+ T cells had significantly increased Th1 (IFNγ) and Th2 (IL-4, IL-5, IL-13) cytokine production potential during patent schistosome infection, at a greater magnitude than observed in pre-patent infection." (PMID 37012228, 2023). "We could not observe significant differences in mb-TLR2 expression from PBMC CD4 and monocyte populations during the infection." (PMID 38140264, 2023). "However, interference with translocation of late endosomes into the NR, or formation of type II NEIs, prevents productive infection as demonstrated in CD4+ T cells." (PMID 37563144, 2023). "Overall, because CD4 and CCR5 are HIV primary coreceptors, the use of CD4+ T cells for the CAR technology may enhance the risk of infection of CAR-T cells." (PMID 36992496, 2023). "Furthermore, CD4+ TRM cells persist in the lungs of humans for up to 10 months after infection with SARS-CoV-218." (PMID 37179389, 2023). "That is not to say that innate immune cells do not remove infected red blood cells and free merozoites, but rather that the efficiency of this process depends upon help from the adaptive immune system (including CD4+ T cells and antibodies), which occurs later in infection." (PMID 37646037, 2023). "Moreover, our study revealed that CRF01_AE, age, and history of concurrent infection were adverse factors for the recovery of CD4+ T cell count during HAART." (PMID 37152735, 2023). "Depletion of both CD4+ and CD8+ T-cells resulted in prolonged lethargy compared to isotype or CD8-depleted mice further suggesting CD4+ T-cells may contribute to control of the infection." (PMID 37866114, 2023). "Nevertheless, CD4+ CTLs constitute a minor population of CD4+ T cells (mainly represented by T helpers) and have been described as primarily targeting NP and M antigens upon infection with the influenza virus." (PMID 38140152, 2023). "Additionally, following infection, only CD8+ CD45R0+ cells were recovered, and it was demonstrated that the loss rate of CD4+ lymphocytes depended on the inoculated strain." (PMID 36680271, 2023). "Furthermore, the Langerhans cells in the vagina and foreskin transport viral particles to the local lymphatics, where they present the viruses to the CD4+ T cells in the process of infecting them and spreading the infection." (PMID 37408185, 2023). "Therefore, we analyzed the ratio of spleen CD4+:CD4+Foxp3+ cells and found it to be significantly increased in the prime-boost vaccinated mice, which implies a better control of the infection than in the BCG-only vaccinated mice." (PMID 37108602, 2023).
infection (continued). "Thus, based on this dichotomy, it will be essential to characterize the CD4+ T cell effector subpopulations and their kinetics following infection of CVB3 in our mouse model." (PMID 38274806, 2023). "However, during the chronic stage of infection, the levels of CD4 remained unaltered and significantly decreased in infected RD-fed and infected MFD-fed mice, respectively, compared to RD-fed uninfected mice." (PMID 36676177, 2023). "Moreover, antagonizing C5aR significantly inhibited TNT formation in DCs as well as DC/CD4+ T-cell co-cultures and lowered the already decreased productive infection in co-cultures." (PMID 35204813, 2022). "CD8+ T cell responses can be modulated by CD4+ T helper cells, so we investigated whether burn injury impacted the numbers, cytokine expression or activity of these cells after infection." (PMID 35505970, 2022). "Additionally, we recommend that future studies should closely monitor changes in parasite genotypes and chronicity of infection over a longer study duration to better track changes in CD4+ T-cell counts." (PMID 36189366, 2022). "HTLV-1 infects DCs and uses them to propagate infection to its target cells, CD4+ T cells." (PMID 36146843, 2022). "In addition to help B cell and antibody responses, eliciting broad and long-lasting antiviral immunity requires the enrollment of CD4+ T cells and the generation of effective T cell memory essential for protection against future infections." (PMID 36341425, 2022). "Infection with Y induced 2- to 13-fold increases in expression of cytokines and T cell markers tested in brain and thymus (except CD4 mRNA in thymus) at 5 and 7 days pi (3 and 5 days pi for IFN-γ response in brain; 7 days pi for CD8 expression in brain) (P<0.05), relative to infection with PS." (PMID 36016955, 2022). "To explore this hypothesis, we performed infection assays in CD4+ T cells using free viral particles and evaluated the transcriptional expression of the viral restriction factors SAMHD1, TRIM5, and APOBEC3G." (PMID 35802715, 2022). "When analyzing the frequency of CD4+ cells, it was observed that IL-17RA-/- 0dpi mice showed an increase in the frequency of CD4 T lymphocytes compared to WT 0dpi and that after infection there was a reduction in the frequency of these cells in the BAL in IL-17RA-/- mice." (PMID 35844540, 2022). "In such a setting, persistent infection of CD4 T cells could result from the infection of cytokine activated cells that surround the immune response foci, which can be defined as “immunologic bystanders”." (PMID 35895672, 2022). "In addition, the expression of CD69 molecules associated with T cell activation in CD3+CD4+ T cells and CD3+CD8+ T cells was also opposite to the trend of MDSCs during infection of S. japonicum (p < 0.05)." (PMID 36279265, 2022). "One study utilizing Plasmodium chabaudi chabaudi demonstrated that engraftment of wildtype but not IL-10-deficient CD4+ T cells protected Rag-/- mice from serious weight loss, hypothermia, and mortality following infection." (PMID 36389662, 2022). "Additionally, we reported that AMD3100 or CXCL12 (the CXCR4 natural ligand) fully inhibited infection of primary CD4+ T cells by cell-free X4-1 Env-pseudotyped viruses (, and here)." (PMID 35622876, 2022). "Since the baseline CD4 count directly reflected immune status, the early onset of infection could facilitate early treatment, thus prolonging the survival time." (PMID 36339239, 2022). "Interestingly, DC-SIGN and unesterified membrane cholesterol are pivotal for macrophage-mediated infection of CD4+ T cells." (PMID 35844525, 2022). "Similarly, CD4 T cells in T-bet-deficient mice infected with Toxoplasma gondii retain the capacity to generate a prominent population of CD4 T cells producing IFN-γ, although these mice were still highly susceptible to infection." (PMID 35196366, 2022).